NOS2 (nitric oxide synthase 2)
Diseases named in the same sentence as NOS2 in open-access papers (continued):
Sharing a sentence is not in itself a finding about the gene and the disease.
infection (continued). "Whilst, NOS1 and NOS3 are involved in the immune response, another isoform of NOS called inducible NOS (NOS2) is responsible for a much greater expression of NO in response to injury or infection." (PMID 19309520, 2009). "One example is nitric oxide synthase 2 (NOS-2), which exhibits a species-specific pattern of expression in response to infection or pro-inflammatory challenge." (PMID 17686182, 2007). "In the time course infection study, the kinetics of urinary NOx excretion are reflected by Nos2 gene expression in colonic mucosal with a small 1.6-fold induction at day 3 p.i. and a 4 fold induction at day 6 p.i.." (PMID 17850650, 2007). "This discrepancy may be explained by the infection and the well-known IL-1β-mediated regulation of NOS2 expression via ERK1/2 and STAT1α signaling pathways." (PMID 41415272, 2025). "In concurrence with the pro-inflammatory gene expression, M1 macrophages expressing IL-1β, Tlr2, and Nos2 clustered around Candida, while despite higher expression of anti-inflammatory genes, M2 macrophages were largely omitted from within the infection niche and rather present around it." (PMID 40586608, 2025). "After determining the effect of the infection of BMMΦ and neonatal mouse cardiomyocytes with two different T. cruzi isolates in the metabolism of L-arginine through NOS2 and arginases, we proceeded to analyze the effect of the enzymes in the survival of parasites inside the cells." (PMID 39452749, 2024). "(E) In vitro infection of unpolarized (M0) bone-marrow-derived murine macrophages (BMDMs) resulted in a down-regulation of TRM-associated marker Mrc1 and an upregulation of M2-like markers Nos2 and Arg1." (PMID 38767331, 2024). "NOS2 (iNOS) is inducible and expressed at a higher level in response to infection or inflammation." (PMID 38539811, 2024). "Intriguingly, genes such as Ifi204, Irgm1/2, Nos2, Gbp3/7, Usp18, Irf7, Stat1, and Isg15, which were upregulated in response to infection in cells treated with siR_Ctrl, showed decreased upregulation in cells treated with siR_Nostrill following infection." (PMID 39040107, 2024). "However, a significantly increased expression of TNFA and NOS2 was noticed only at 4 weeks post infection, compared to uninfected animal lungs." (PMID 38338937, 2024). "Interestingly, not only infection with viable PA but also treatment with heat-inactivated bacteria (HI PA) led to a significant increase of NOS2 mRNA levels." (PMID 39691712, 2024). "Furthermore, during the acute infection stage, the genes Arg1, Arg2, Ckb, and Nos2 displayed upregulation and were found to be enriched in the arginine and proline metabolism pathway." (PMID 38229193, 2024). "Thus, we analyzed if infection with two T. cruzi isolates with different degrees of virulence resulted in a differential expression and activity of NOS2 and Arg-1 in BMMΦ of CD1 mice." (PMID 39452749, 2024). "In addition, similar levels of significantly induced expression of TNFA, IFNG, and NOS2 were noted at 4 weeks post infection, compared to the uninfected control lungs." (PMID 38338937, 2024). "Furthermore, we identified 1959 commonly expressed DEmRNAs, including IL27, Nos2, and Cxcr2, across two infection stages." (PMID 38229193, 2024). "Indeed, infected Acod1−/− mice expressed higher mRNA levels of Il6, IFNγ, Nos2 and Gbp1 than wild‐type controls in the lungs, but also in the spleen, after intratracheal infection." (PMID 36479617, 2023). "In addition, if we prepared bacteria by first sonicating and then using a 5μmF (so/5μmF), the expression changes resembled so/sp infection, with marked upregulation of Il1b, Il6, Nos2, and Tnf." (PMID 36852737, 2023). "Furthermore, flow cytometry was performed for validation, and it yielded consistent conclusions, a notable increase in NOS2+ monocytes was observed post-infection." (PMID 37638012, 2023). "Also, under putrescine supplementation Nos2 levels increased at 4h of infection compared to uninfected macrophages." (PMID 37000792, 2023).
infection (continued). "When we examined macrophage gene expression after infection with ∆ppsD by qPCR, we found that expression of Il1b, Il6, Nos2, and Tnf was significantly increased compared to infection with WT Mtb, consistent with the idea that PDIM reduces inflammatory signaling." (PMID 36852737, 2023). "Brain and spinal cords from mock and RSA59 infected 4–5-week-old MHV-free C57BL/6 mice (WT) and NOS2-/- mice were harvested at different disease phases post infection (p.i.)(day 5/6-acute, day 9/10-acute-adaptive and day 30-chronic phase) and compared for pathological outcomes." (PMID 36966345, 2023). "The production of NO by NOS2 (in micromolar amounts) is much higher and more sustained than by other NOSes, thereby making NOS2 an important player in regulating inflammation and infection." (PMID 38106413, 2023). "Nos2 expression remained similar across all infection groups." (PMID 35482787, 2022). "infection of Nos2−/− mice with M.tb H37Rv developed the severe neurological symptoms and induced a high expression of adhesion molecules, chemokines, and inflammatory cytokines in the brain, consistent with the infiltration of inflammatory cells and pathological changes." (PMID 35073927, 2022). "RT‐qPCR experiments showed that Kp52145 infection increased the levels of the M(Kp) markers arg1, il10, nos2, the ISG isg56 and ido in THP‐1 cells in a STAT6‐dependent manner because the STAT6 inhibitor AS1517499 abrogated Klebsiella‐mediated upregulation of these M(Kp) markers." (PMID 36337046, 2022). "Among those, the highest fold changes in the infected liver were for Nos2 (log2FC > 10), Ifnγ (log2FC > 8), Tnf (log2FC > 5), and Il21 (log2FC > 6.6), denoting the sustained high inflammatory environment in this tissue during late infection." (PMID 35384718, 2022). "infection of Nos2−/− mice with H37Rv creates a murine CNS-TB model that resembled human CNS-TB immunopathology, exhibiting the worst neurobehavioral score and with a high and early mortality reflecting disease severity and its associated neurological morbidity." (PMID 35073927, 2022). "infection of Nos2−/− mice with H37Rv strain creates a better CNS-TB model than the i.v. route of infection as it exhibited more pronounced brain inflammation as shown by the higher expression of pro-inflammatory cytokines, Th1 chemokines and neutrophil chemoattractants." (PMID 35073927, 2022). "Notably, we found that the expression of specific markers of M1 type microglia (Aif1, Cd86, Cd40, Ccl2, Ccr2, Cx3cr1, IL-1β, IL-6, and NOS2) was elevated post infection." (PMID 36618398, 2022). "Even at the chronic stage of infection (42dpi), which is expected to have a M2 macrophages bias, cells from monocyte-derived macrophage subpopulation are Nos2/Arg1 double positive, indicating a mix phenotype that cannot be categorized along the M1/M2 paradigm lines." (PMID 36420267, 2022). "In addition, miR-302d has also been described as a regulator of NOS2 expression, and melatonin treatment or miR-302d-3p or miR-30e-5p inhibition enhanced NOS2 mRNA expression and NO production, decreasing macrophages infection." (PMID 34218829, 2021). "In comparison, the present study observed a similar 1,25(OH)2D3 dependent increase in nitric oxide production, but a disparate pattern of NOS2 expression was observed in which there was a significant decrease in all infection status groups following the same 1,25(OH)2D3 treatment." (PMID 35111692, 2021). "In addition, HIF-1α KO mice infected with B. abortus exhibited reduced frequency of splenic CD80+ and NOS2+ inflammatory macrophages in comparison with HIF-1α WT during the early phase of the infection." (PMID 33989349, 2021). "In addition, increasing evidence supports that GTPase family represents a new IFN-γ-dependent, nitric oxide synthase 2-independent pathway in the control of pathogen infection." (PMID 34295340, 2021).
infection (continued). "Moreover, in this in vivo model of infection, daily treatment (orally administered) with 25 mg/kg/day Bzl induced a significant decrease in IL-1β, IL-6 and NOS2 in the heart and CK activity in serum, to normal levels." (PMID 34925364, 2021). "Knockdown of Prdm1 in IEC4.1 cells resulted in enhanced antimicrobial activity against C. parvum infection induced by IFN-γ, with a significant further decrease in the infection burden and a further increase in the expression of defense genes, including Nos2, Ido1, and Csf2." (PMID 34488445, 2021). "Analysing the proteome of RAW 264.7 (a murine macrophage cell line) treated with GC7 prior to infection with H. pylori revealed that, among other proteins, NOS2 was downregulated leading to a decline in NO2−, the stable metabolite of NO derived from NOS2 activity." (PMID 34952646, 2021). "However, in each case, U288 strains (i) colonised the mouse caecum to a greater level, (ii) induced higher levels of CXCL1 and NOS2 transcripts, and iii) triggered a more severe pathology, compared to that resulting from infection with ST34 strains." (PMID 33893390, 2021). "Notably, M. avium displays increased virulence during infections of wild-type mice than when infecting NOS2 knockout mice." (PMID 34832521, 2021). "Moreover, the frequency of NOS2+ in HIF-1α KO macrophages was also diminished at the later phase of infection." (PMID 33989349, 2021). "In addition to increasing Nos2 expression, HS-induced Nfat5 expression facilitates autolysosome formation upon infection, which is critically required for HS-boosted antibacterial activity directed against E. coli." (PMID 32569301, 2020). "Moreover, genes such as Ifr9, Ifr8, Ifr7, CSF2RA, STAT1, and STAT2 were expressed to a greater extent in the PmQ infection group than PmCQ2, and Il22, Il6, Nos2, Ccl4, Ccl5, Ifr1, Socs1, and Socs3 were increased only in PmQ infected chickens rather than PmCQ2." (PMID 32851030, 2020). "In addition, IL-22 deficient mice (Il22−/−) succumbed to infection, which correlated with reductions in the numbers of CD4+ IFN-γ+ T cells, reduced IFN-γ levels, and diminished nitric oxide synthase type 2 (NOS2) expression in the lungs." (PMID 32517114, 2020). "During the late stages of infection, ARG1 contributes to control of prolonged hyperinflammation; ARG1 also plays a role in regulating the progression of lung immunopathology in Mtb-infected, Nos2-deficient mice." (PMID 32903583, 2020). "Additionally, melatonin treatment or miR-30e-5p and miR-302d-3p inhibition increased nitric oxide synthase 2 (Nos2) mRNA expression levels and nitric oxide (NO) production, altering the macrophage activation state and reducing infection." (PMID 30949455, 2019). "Similarly, treatment of bMDM with IL10 siRNA enhanced expression of IL1B, TNF, IL6, IFNG and NOS2 induced by G18 infection." (PMID 31527895, 2019). "The increased levels of citrulline can be a consequence of citrulline production via L-arginine conversion by host arginine deaminase, or ornithine conversion by ornithine transcarbamilase (OTC); subsequently, the infection reduces Nos2 mRNA and NOS2 protein levels and NO production." (PMID 31835767, 2019). "In contrast, melatonin increased Nos2 mRNA expression and NO production during infection." (PMID 30949455, 2019). "Moreover, the absence of signals mediated by MyD88, TLR2, or TLR4 reduced nitric oxide synthase 2 (Nos2) mRNA expression during infection." (PMID 30555476, 2018). "The fact that Arg-1 and NOS2 coexist in the here examined T. cruzi-infected IL-13tg mice may favor a role of MDSC in the outcome of infection." (PMID 30555475, 2018). "PBMC NOS2 expression was altered by diet × infection (p = 0.001)." (PMID 30778359, 2018). "To ascertain whether infections of lin− cell populations were particular to dermal infection with M. tuberculosis, we examined the bone marrow of wt and Nos2−/− mice 28 days after aerosol challenge with M. tuberculosis." (PMID 29471332, 2018).
infection (continued). "Nos2 is highly expressed during pathogen infection and accumulates nitric oxide (NO).NOS2 is mainly responsible for NO production, but it is further able to produce ROS, when concentrations of tetrahydrobiopterin or the co-substrate L-arginine is available in low quantities." (PMID 30283451, 2018). "Recognition by TLRs induced antiparasitic activity and the production of pro-inflammatory cytokines, such as IL-1, IL-6, TNF, IL-12 e IFN-γ, which also could influence the rate of NOS2/ARG1 during infection." (PMID 29379478, 2017). "However, concomitant with the decrease of Fpn, an increase in the mRNA expression of Nos2 gene was observed with ST infection in both WT and Hamp−/− liver." (PMID 28507548, 2017). "However, high Arg1 expression preceded the increased induction of NOS2 and at early time points of infection mycobacteria were mostly found in cells positive for Arg1." (PMID 29176982, 2017). "Thus, activation of inflammasomes, as well as the transcriptional activation of Nos2 during infection, must be tightly regulated." (PMID 28150715, 2017). "These predictions can be taken as evidence of L-arginine-NO pathway regulation by miRNAs during infection with La-WT L. (L.)amazonensis and are corroborated by the data obtained during La-arg− infection, such as the increased Nos2 mRNA expression, NOS2 and NO production after 4 h of infection." (PMID 28276497, 2017). "Blockade of de novo protein synthesis strongly inhibited Nos2 induction following macrophage infection with the BTB 02-171 strain, indicating that specific mediators produced upon TLR4 stimulation were required to induce Nos2 transcription in infected macrophages." (PMID 27849167, 2016). "Infection with C. concisus UNSWCD induced an oxidative stress response in IECs, with a range of metallothionein-encoding transcripts found to be upregulated, in addition to nitric oxide synthase 2 (NOS2) and glutathione peroxidase 1 (GPX1)." (PMID 27677841, 2016). "To date, very little research has examined how Giardia infections modulate macrophage phenotypes during infection, and only one study has shown that in vivo Giardia assemblage B infections result in the accumulation of macrophages positive for both NOS2 and Arginase-1." (PMID 26569316, 2015). "However, while the role of NOS2 and phox in infection by L. major has been unequivocally shown by several authors, its role in infection by visceralizing Leishmania species is not so clear." (PMID 26684322, 2015). "More significantly, Ifng and Nos2 (encoding iNOS) transcripts were elevated approximately 200-fold and 1000-fold, respectively, in latently infected control and HOIL-1 KO mice, and further induced by 3 hr after infection with Listeria." (PMID 25599590, 2015). "In contrast, the marker for the classically activated pathway, NOS-2, was unaltered by infection." (PMID 24465430, 2014). "However, the effects on induction of ccl20, nos2 and odc were much more pronounced upon infection with the isolate GS than with WB and P15." (PMID 24228819, 2013). "Nitric oxide synthase 2 is deleterious for the host in this experimental mouse infection model." (PMID 23978258, 2013). "Third we found that at the site of visceral infection (spleen) in hamsters there is dominant expression of arg1, such that the arg1 to NOS2 ratio in hamsters with progressive disease was thousands-fold greater than the ratio observed in mice, which are able to control the infection." (PMID 22275864, 2012). "In addition to the adaptive T-cell response, TNF production and expression of inducible nitric oxide synthase (iNOS or NOS2) by macrophages aid in clearing the infection." (PMID 21811511, 2012). "Furthermore, decreased IL-10 expression upon infection with 10/84ΔcylE bacteria correlated with increased IL-12p40 and NOS2 mRNA." (PMID 22829768, 2012).
infection (continued). "There was not a difference in the percentage of infected cells among untreated wild type and nos2/gp91−/− macrophages, suggesting that nos2/gp91−/− cells were not more susceptible to SchuS4 infection compared to wild type cells." (PMID 20523903, 2010). "During Th1 responses, CAM-derived Arg1 antagonizes NOS2 activity, which promotes infection by intracellular pathogens, while in Th2 responses Arg1-expressing AAMs contribute to the resolution of chronic Th2-driven inflammation and fibrosis by functioning as suppressor cells." (PMID 19360123, 2009). "Nos2 gene expression in colonic mucosa was below detection levels in the dietary infection study." (PMID 17850650, 2007). "Notably, key inflammatory mediators, such as interleukin-1 (Il1a) and nitric oxide synthase 2 (Nos2) were up-regulated after infection in obese ferrets, possibly leading to extensive inflammatory damage of the respiratory epithelium as observed in histopathology." (PMID 38728395, 2024). "Hence, future studies need to choose wild-type Mtb to establish animal infection models and alveolar macrophages for in vitro experiments to explore the regulation function of Nos2 expression on NO, ROS, and Defb1, which will resolve these limitations of the study." (PMID 39412514, 2024). "Nos2, also termed iNOS, is a homodimeric enzyme that is induced by immune stimulation in an independent of intracellular Ca2+ manner and plays an important role in infection, inflammation, immune regulation, and the control of intracellular bacterial pathogen infection." (PMID 39412514, 2024). "In the present study, we tested, in an in vitro murine model, the hypothesis that T. cruzi isolates with variable virulence degrees differentially regulate L-arginine metabolism through arginase and NOS2, influencing the infection course and severity in the host." (PMID 39452749, 2024). "In addition to the 72 hpi timepoint used for RNA-seq, we found that infection with so/sp Mtb elicited significantly higher levels of expression of Il1b, Nos2, Il6, and Tnf at 6 and 24 hpi by qPCR compared with 5μmF preparations, with the greatest difference seen early in infection." (PMID 36852737, 2023). "Notably, IL-1β has been identified as a significant signaling factor for host resistance against infection, as this cytokine transmits signals through IL-1R and myeloid differentiation primary response protein (MyD) 88, leading to the induction of NOS2-mediated nitric oxide (NO) production." (PMID 38097942, 2023). "Of these, a lncRNA, named NR_045064, could reduce infection burden of parasites in murine intestinal epithelial cells in vitro and in the enteroids of neonatal mice by promoting expression of host defense genes (e.g. Csf2, Nos2, and Cxcl2)." (PMID 35999576, 2022). "A higher NOS2 activity during infection might also confer protection." (PMID 34777283, 2021). "The impaired growth of M. tuberculosis Δrip1 in the lung was dramatically reversed in the absence of NO, such that Δrip1 lung titers in NOS2-deficient animals were 100-fold higher than in wild-type mice at 3 weeks and 10,000-fold higher at 8–10 weeks post infection." (PMID 34003742, 2021). "However, NOS2 mRNA levels were only affected by IL10 siRNA during G18 infection." (PMID 31527895, 2019). "Genetic variation in NOS2 promoter region may play a very important biological role in host defense mechanisms against malaria pathology by enhancing anti-oxidants enzymes and stimulating the infection induced biochemical cascade against plasmodium pathology." (PMID 30118498, 2018). "In addition, inflammatory marker NOS2-positive macrophage number was dramatically elevated in control and H. polygyrus-infected mice following LPS injection or Salmonella Typhimurium infection, showing the emergence of infection." (PMID 29343442, 2018).